TEKTIP1 (tektin bundle interacting protein 1)
Description:
Microtubule inner protein (MIP) part of the dynein-decorated doublet microtubules (DMTs) in cilia axoneme, which is required for motile cilia beating. Located at the center of the tektin bundle where may function to recruit tektins or stabilize the bundle.
Synonyms: C19orf71; LOC100128569
Tractability: Antibody: the Human Protein Atlas places it where antibodies can reach.
Gene: Protein-coding gene on chromosome 19 (3,539,171 to 3,544,030, forward strand). Ensembl gene ENSG00000183397.
Subcellular location: Cytoplasm, cytoskeleton, cilium axoneme; Cytoplasm, cytoskeleton, flagellum axoneme
Subcellular location (Human Protein Atlas): Cytosol; Plasma membrane; Endoplasmic reticulum
Gene Ontology:
Biological process: flagellated sperm motility
Cellular component: axonemal A tubule inner sheath; axonemal microtubule; sperm flagellum; axoneme
Genetic constraint (gnomAD): Loss-of-function variants: 28 observed, 19.75 expected, observed/expected ratio (o/e) 1.42, 90% interval 1.05 to 1.86. The synonymous counts are far from expectation, so gnomAD's model fits this gene poorly and the ratio says little. Missense variants: 424 observed, 275.44 expected, observed/expected ratio (o/e) 1.54, 90% interval 1.42 to 1.67. Synonymous variants: 184 observed, 123.19 expected, observed/expected ratio (o/e) 1.49, 90% interval 1.32 to 1.69.
Homologues: Orthologues: chimpanzee TEKTIP1 (98% identical), macaque TEKTIP1 (88% identical), dog TEKTIP1 (77% identical), pig TEKTIP1 (74% identical), guinea pig TEKTIP1 (58% identical), mouse Tektip1 (57% identical), rat Tektip1 (57% identical).
Diseases named in the same sentence as TEKTIP1 in open-access papers:
TEKTIP1 is named in the same sentence as 3 diseases in open-access papers, as found by Europe PMC text mining. Sharing a sentence is not in itself a finding about the gene and the disease. The quoted sentences say what the papers report.
asthenospermia (1 paper, 2024). "Whole-exome sequencing of a large cohort of infertile men primarily with asthenospermia will be useful to screen any pathogenic mutations in TEKTIP1." (PMID 38448737, 2024).
male infertility (1 paper, 2024). The inability of the male to effect fertilization of an ovum after a specified period of unprotected intercourse. "Our animal study suggests that TEKTIP1 is essential for mouse sperm motility and that its deficiency may be a potential genetic cause of human male infertility with MIVA." (PMID 38448737, 2024). "However, clinical evidence linking TEKTIP1 to male infertility is still lacking." (PMID 38448737, 2024).
TEKTIP1 also shares sentences with these, for which no sentence is quoted: infertile (1 paper).